AQP4 (aquaporin 4)
Description:
Forms a water-specific channel. Plays an important role in brain water homeostasis. It is involved in glymphatic solute transport and is required for a normal rate of water exchange across the blood brain interface. Required for normal levels of cerebrospinal fluid influx into the brain cortex and parenchyma along paravascular spaces that surround penetrating arteries, and for normal drainage of interstitial fluid along paravenous drainage pathways. Thereby, it is required for normal clearance of solutes from the brain interstitial fluid, including soluble beta-amyloid peptides derived from APP. Plays a redundant role in urinary water homeostasis and urinary concentrating ability (By similarity).
Synonyms: AQP-4; MIWC; hAQP4; MLC4; WCH4
Tractability: Antibody: UniProt places it where antibodies can reach, with high confidence; its Gene Ontology location is reachable by antibodies, with high confidence; UniProt predicts a signal peptide or a membrane-spanning region; the Human Protein Atlas places it where antibodies can reach. PROTAC: its protein half-life has been measured.
Target class: Ion channel; Other ion channel; Aquaporin; Water-specific aquaporin
Gene: Protein-coding gene on chromosome 18 (26,852,043 to 26,865,771, reverse strand). Ensembl gene ENSG00000171885.
Subcellular location: Cell membrane; Basolateral cell membrane; Endosome membrane; Cell membrane, sarcolemma; Cell projection
Subcellular location (Human Protein Atlas): Plasma membrane; Cell Junctions
Pathways (Reactome):
Transport of small molecules: Passive transport by Aquaporins; Vasopressin regulates renal water homeostasis via Aquaporins
Gene Ontology:
Molecular function: protein binding; water channel activity; channel activity
Biological process: cellular response to type II interferon; intracellular water homeostasis; multicellular organismal-level water homeostasis; protein homotetramerization; water transport; cerebrospinal fluid circulation; renal water homeostasis; transmembrane transport
Cellular component: cell junction; cytoplasm; external side of plasma membrane; plasma membrane; sarcolemma; astrocyte end-foot; basolateral plasma membrane; endosome membrane; extracellular region; membrane
Genetic constraint (gnomAD): Loss-of-function variants: 18 observed, 29.55 expected, observed/expected ratio (o/e) 0.61, 90% interval 0.42 to 0.9. The upper end of that interval is the gene's LOEUF score, 0.9, which puts it in group 3 of 6, group 1 being the genes least tolerant of losing a copy. Missense variants: 412 observed, 432.9 expected, observed/expected ratio (o/e) 0.95, 90% interval 0.88 to 1.03. Synonymous variants: 141 observed, 151.92 expected, observed/expected ratio (o/e) 0.93, 90% interval 0.81 to 1.07.
Homologues: Orthologues: chimpanzee AQP4 (99% identical), guinea pig AQP4 (98% identical), pig AQP4 (96% identical), rabbit AQP4 (96% identical), dog AQP4 (95% identical), mouse Aqp4 (93% identical), rat Aqp4 (93% identical), macaque AQP4 (89% identical), tropical clawed frog aqp4 (73% identical), zebrafish aqp4 (61% identical), Drosophila melanogaster Eglp2 (26% identical), Drosophila melanogaster Eglp4 (25% identical), and 2 more. Paralogues in human: AQP5 (40% identical), AQP2 (39% identical), AQP1 (36% identical), MIP (35% identical), AQP6 (34% identical), AQP7 (21% identical), AQP8 (20% identical), AQP9 (20% identical), AQP3 (20% identical), AQP7B (19% identical), AQP10 (18% identical).
Diseases named in the same sentence as AQP4 in open-access papers:
AQP4 is named in the same sentence as 496 diseases in open-access papers, as found by Europe PMC text mining. Sharing a sentence is not in itself a finding about the gene and the disease. The quoted sentences say what the papers report.
neuromyelitis optica spectrum disorder (861 papers, 2008 to 2026). "Neuromyelitis optica (NMO) is an autoimmune disorder characterized by autoantibodies against the astrocyte water channel aquaporin-4 (AQP4) that cause demyelination in the optic nerves and spinal cord." (PMID 41480772, 2026). "Neuromyelitis optica spectrum disorder (NMOSD) is a rare autoimmune disease associated with aquaporin-4 antibodies (AQP4-IgG)." (PMID 40247675, 2025). "AQP4 has been implicated as having an important triggering role in the development of neuromyelitis optica (NMO), a neurologic disease characterized by inflammation of the optic nerve and spinal cord." (PMID 40282759, 2025). "Neuromyelitis optica spectrum disorder (NMOSD) is an autoimmune disease driven by pathogenic antibodies targeting aquaporin-4 (AQP4), leading to relapsing optic neuritis and myelitis." (PMID 40257801, 2025). "Neuromyelitis optica spectrum disorder (NMOSD) is a rare autoimmune astrocytopathy associated with aquaporin‐4 antibodies (AQP4‐IgG), characterised by a highly relapsing and disabling disease course." (PMID 40087846, 2025). "Neuromyelitis optica spectrum disorder (NMOSD) is an inflammatory disease of the central nervous system (CNS) characterized by pathogenic autoantibodies directed against aquaporin-4 (AQP4-IgG)." (PMID 41459546, 2025). "Pathogenic autoantibodies in neuromyelitis optica bind three multiply presented loops on arrays of human aquaporin-4." (PMID 39982991, 2025). "Neuromyelitis optica spectrum disorder associated with aquaporin-4-antibodies (AQP4-NMOSD) is an autoimmune disease of the CNS with a high risk of visual, motor and sensory disability secondary to optic neuritis (ON) and transverse myelitis (TM) attacks." (PMID 41209341, 2025). "Among autoimmune diseases, numerous alterations in AQP expression have been documented, notably in the salivary glands of Sjögren’s syndrome or the association with neuromyelitis optica mediated by AQP4." (PMID 40072108, 2025). "Anti‐AQP4 antibodies are associated with neuromyelitis optica spectrum disorder; antibodies against myelin oligodendrocyte glycoprotein (MOG) are found in a similar demyelinating disorder." (PMID 40781762, 2025). "Aquaporin‐4‐IgG‐positive neuromyelitis optica spectrum disorder (AQP4‐IgG+ NMOSD) can cause significant disability after a single attack." (PMID 40492480, 2025). "Neuromyelitis optica spectrum disorder (NMOSD) is an autoimmune neuroinflammatory disease of the central nervous system associated with aquaporin-4-immunoglobulin-G (AQP4-IgG)." (PMID 41562061, 2025). "Myelin oligodendrocyte antibody‐associated disease (MOGAD) and aquaporin‐4 antibody (AQP4‐IgG) seropositive neuromyelitis optica spectrum disorder (AQP4+ NMOSD) are auto‐antibody‐associated CNS inflammatory diseases." (PMID 39901660, 2025). "Neuromyelitis optica spectrum disorder (NMOSD) is a severe autoimmune neurological inflammatory disease driven mainly by pathogenic aquaporin-4 antibodies (AQP4-IgG antibodies)." (PMID 40843677, 2025). "A significant subset of NMOSD cases, also referred to as Devic’s disease, is associated with antibodies targeting aquaporin-4 (AQP4), a water channel protein predominantly expressed in astrocytes." (PMID 41057549, 2025). "Detection of antibodies against aquaporin-4 (AQP4-IgG) and myelin oligodendrocyte glycoprotein (MOG-IgG) is essential for diagnosis of AQP4-IgG+ neuromyelitis optica spectrum disorder and myelin oligodendrocyte glycoprotein antibody-associated disease." (PMID 40933287, 2025). "For instance, aquaporin-4 antibodies are recognized as a causal factor in seropositive Neuromyelitis Optica Spectrum Disorders (NMOSD)." (PMID 41464133, 2025). "* Anti-aquaporin-4 antibody is included in the diagnostic criteria for neuromyelitis optica spectrum disorder (NMOSD)." (PMID 40018473, 2025).
neuromyelitis optica spectrum disorder (continued). "Background and aims: Little is known about the impact of myelin oligodendrocyte glycoprotein antibody‐associated disease (MOGAD) and aquaporin‐4‐IgG‐seropositive neuromyelitis optica spectrum disorder (NMOSD‐AQP4+) on cognitive performance (CP)." (PMID 40542581, 2025). "Neuromyelitis optica spectrum disorder (NMOSD) is a neuroinflammatory disease caused by aquaporin-4 IgG antibodies, which damage astrocytes and trigger inflammation." (PMID 40701519, 2025). "Neuromyelitis optica spectrum disorder (NMOSD) is an autoimmune disease of the central nervous system often associated with aquaporin-4-immunoglobulin-G (AQP4-IgG), which activate the complement system, and it can lead to progressive neurological disability." (PMID 41562061, 2025). "Serological testing for neuromyelitis optica spectrum disorder (NMOSD)-associated aquaporin-4 (AQP4) antibodies and myelin oligodendrocyte glycoprotein (MOG) antibodies also returned negative results." (PMID 40896010, 2025). "recently demonstrated that B cells endogenously express AQP4, an autoantigen linked with neuromyelitis optica, in response to CD40 stimulation." (PMID 40625741, 2025). "Hyperpermeability of the vascular endothelium is a hallmark of the aquaporin-4-autoantibody mediated autoimmune disease, neuromyelitis optica spectrum disorder (NMOSD)." (PMID 39457022, 2024). "Characterized as an inflammatory CNS syndrome, NMOSD, also known as Devic disease, is associated with the serum AQP4-IgG antibodies and is considered an autoimmune demyelinating astrocytopathy." (PMID 38618469, 2024). "Aquaporin-4 immunoglobulin G (AQP4-IgG) antibody-positive neuromyelitis optica spectrum disorders (NMOSD) are frequently associated with other autoimmune disorders, including systemic lupus erythematosus (SLE)." (PMID 37962590, 2024). "MOGAD is a demyelinating disease of the CNS with clinical, demographic, and radiological features different from multiple sclerosis (MS) and from aquaporin-4 (AQP4) autoantibody-associated neuromyelitis optica spectrum disorder (NMOSD)." (PMID 38010585, 2024). "Aquaporin-4 antibodies (AQP4-Abs) are a diagnostic marker for patients with a demyelinating disease called neuromyelitis optica spectrum disorder (NMOSD)." (PMID 38887290, 2024). "Neuromyelitis optica spectrum disorder (NMOSD) is an uncommon demyelinating disorder of the central nervous system (CNS) caused by the action of the anti-AQP4 antibodies." (PMID 39872531, 2024). "The HLA-DQB*05:02 allele is highly associated with AQP4-positive Neuromyelitis Optica Spectrum Disorder (NMOSD) in the Chinese population and is a high-risk factor for the onset of Myasthenia Gravis, particularly in MuSK-related Myasthenia Gravis." (PMID 38765268, 2024). "Neuromyelitis optica spectrum disorder is an autoimmune astrocytopathy characterized by the presence of autoantibodies targeting AQP4, thereby resulting in astrocyte loss and demyelination of the CNS." (PMID 38818518, 2024). "27,31 Brain MRI can indicate multiple sclerosis or other inflammatory demyelinating disorders (i.e. AQP4+ neuromyelitis optica spectrum disorder and myelin oligodendrocyte glycoprotein antibody-associated disease)." (PMID 39611182, 2024). "Neuromyelitis optica spectrum disorder (NMOSD) is associated with pathological aquaporin-4 immunoglobulin G (AQP4-IgG), which cause brain damage." (PMID 39457022, 2024). "Aquaporin-4 (AQP4) antibody-associated neuromyelitis optica spectrum disorder (NMOSD) is an antibody-mediated inflammatory disease of the central nervous system." (PMID 38958756, 2024). "Following the discovery that AQP4 serves as a possible autoantigen in neuromyelitis optica, another research has confirmed the loss of AQP4 polarity in chronic-active MS lesions." (PMID 38976012, 2024). "Neuromyelitis optica spectrum disorder (NMOSD) is an autoimmune astrocytopathy caused by the autoantibody of aquaporin-4 (AQP4)." (PMID 38419701, 2024).
neuromyelitis optica spectrum disorder (continued). "The dystonia likely represents painful tonic spasms in Neuromyelitis Optica with AQP4 antibodies, as the association between these two diseases is very strong." (PMID 39651491, 2024). "The AQP4 channel is implicated in CNS pathologies such as neuromyelitis optica spectrum disorder (DMOSD), a demyelinating and inflammatory disease detected in the spinal cord and the optical nerves." (PMID 39043897, 2024). "On a similar note, DENV infection has been associated with the development of neuromyelitis optica spectrum disorder; the serum of patients tested positive for AQP4 antibody." (PMID 36834929, 2023). "In the central nervous system, two major aquaporins (AQPs), AQP1 and AQP4, and their potential involvements have been long implicated in the pathophysiology of many brain disorders such as brain edema and Neuromyelitis optica." (PMID 37047501, 2023). "Neuromyelitis optica spectrum disorder (NMOSD) is a demyelinating disease that causes lesions in areas with abundant aquaporin-4 (AQP4) channels, including the hypothalamus." (PMID 37904479, 2023). "The best-known example of autoimmunity against AQPs concerns the antibodies to AQP4 which are involved in the pathogenesis of neuromyelitis optica spectrum disorder (NMOSD), an autoimmune astrocytopathy, causing also CNS demyelination." (PMID 37629163, 2023). "This peripheral exposure of the CNS AQP4 pool suggests its potential susceptibility as an initial target for circulating AQP4-specific antibodies, particularly in the context of neuromyelitis optica (NMO), a topic warranting further exploration." (PMID 37762642, 2023). "Clinical and CSF findings in patients with AQP4-IgG-positive neuromyelitis optica spectrum disorders (AQP4+NMOSD), MOG-IgG-associated disease (MOGAD), and multiple sclerosis (MS)." (PMID 36419536, 2022). "Neuromyelitis optica spectrum disorders (NMOSDs) are caused by immunoglobulin G (IgG) autoantibodies directed against the water channel aquaporin-4 (AQP4)." (PMID 35666871, 2022). "Neuromyelitis optica spectrum disorders (NMOSD) is a rare autoimmune demyelinating disorder of the central nervous system (CNS) associated with aquaporin-4 (AQP4) in which astrocytopathy is the primary pathology followed by neuroaxonal damage." (PMID 35185873, 2022). "Neuromyelitis optica spectrum disorder (NMOSD), also known as Devic’s disease, causes an inflammatory longitudinally extensive transverse myelitis and optic neuritis, frequently associated with aquaporin-4 IgG1 autoantibodies." (PMID 35053834, 2022). "Neuromyelitis optica (NMO) is an inflammatory demyelinating disease in the central nervous system (CNS) caused by an autoantibody against aquaporin 4 (AQP4), a water channel in astrocytes." (PMID 36058998, 2022). "Spinal cord MRI abnormalities in patients with AQP4-IgG-positive neuromyelitis optica spectrum disorders (AQP4+NMOSD), MOG-IgG-associated disease (MOGAD), and multiple sclerosis (MS)." (PMID 36419536, 2022). "As described, TDLs are associated with MS, but they can occur in neuromyelitis optica spectrum disorders, and testing for AQP4-IgG and MOG-IgG is recommended." (PMID 35418930, 2022). "In humans, loss of AQP4 at perivascular astrocytic endfeet was seen in several brain diseases, including mesial temporal lobe epilepsy, neuromyelitis optica, and ischemic stroke." (PMID 36119130, 2022). "Neuromyelitis Optica Spectrum Disorder (NMOSD), previously called Devic’s disease is an Aquaporin-4-Immunoglobulin G (AQP4-IgG) antibody-associated autoimmune inflammatory disease of the Central Nervous System mostly involving the optic nerve and spinal cord." (PMID 34814882, 2021). "Among autoimmune demyelinating CNS disorders, international consensus diagnostic criteria exist for neuromyelitis optica spectrum disorders (NMOSD) with AQP4 autoantibodies." (PMID 34305787, 2021).
neuromyelitis optica spectrum disorder (continued). "At the same time, the synthetic antibody to AQP4 also benefits a great deal in diseases caused by the autoantibody to AQP4, such as neuromyelitis optica." (PMID 35173581, 2021). "Neuromyelitis optica is an antibody-mediated autoimmune inflammatory disease of the CNS, caused by the loss of aquaporin-4 and GFAP that are mainly expressed by astrocytes." (PMID 34804074, 2021). "In keeping with this, autoantibodies against the astrocytic water channel protein Aquaporin-4 (AQP4) were shown to cause ~80% of occurrences of neuromyelitis optica, an autoimmune condition with a neurodegenerative component." (PMID 34440788, 2021). "We recently found a similar impact of steroid treatment in patients with MS, AQP4-IgG+ neuromyelitis optica spectrum disorder and MOG-IgG-associated disease." (PMID 34108575, 2021). "Neuromyelitis optica spectrum disorder (NMOSD) is an autoimmune inflammatory disease of the central nervous system involving pathogenic autoantibodies against aquaporin-4 (AQP4-IgG)." (PMID 34394101, 2021). "Neuromyelitis optica is caused by an immunoglobulin G autoantibody (AQP4-IgG) that activates the classical complement pathway in the central nervous system." (PMID 34566967, 2021). "Neuromyelitis optica spectrum disorder (NMOSD) is a severe disabling autoimmune disease of the central nervous system (CNS) associated with anti-aquaporin-4 (AQP4)-autoantibody." (PMID 34335563, 2021). "The immunocytochemical and immunoprecipitation data suggested that regions of AQP4 loss in neuromyelitis optica [NMO) spinal cord lesions are deficient in EAAT2." (PMID 32012713, 2020). "Most cases of neuromyelitis optica spectrum disorders (NMOSD) harbor pathogenic autoantibodies against the water channel aquaporin 4 (AQP4)." (PMID 32293546, 2020). "Neuromyelitis optica spectrum disorder (NMOSD) is an immune-mediated inflammatory disease of the central nervous system with aquaporin-4 immunoglobulin G (AQP-4 IgG) as a pathogenic autoantibody." (PMID 33028926, 2020). "In particular, autoantibodies to aquaporin 4 (AQP4) are associated with neuromyelitis optica spectrum disorders (NMOSD)." (PMID 30824481, 2019). "MRI showed a cervical myelitis over more than three vertebral segments up to the lower medulla and Aquaporin-4-antibodies were positive (diagnostic criteria for a Neuromyelitis optica spectrum disorder were fulfilled)." (PMID 30918729, 2019). "Given its clinical utility and the apparent higher incidence and prevalence of MOG Ab-associated demyelination compared to aquaporin-4 (AQP4) Ab-associated neuromyelitis optica spectrum disorders (NMOSD), requests for MOG Ab screening has dramatically risen." (PMID 31481127, 2019). "Brain-reactive antibodies to the water channel protein aquaporin-4 (AQP4) are a hallmark finding in neuromyelitis optica (NMO), a neurological disease that predominantly affects women, many of whom are of childbearing age." (PMID 30057582, 2018). "AQP4 antibodies are pathogenic and diagnostic for neuromyelitis optica spectrum disorder associated with multiple sclerosis (MS)." (PMID 30555637, 2018). "Immunoglobulin G (IgG) autoantibodies against the extracellular domain of aquaporin-4 (AQP4) are likely pathogenic mediators of neuromyelitis optica spectrum disorders (NMOSD)." (PMID 29447335, 2018). "Persuasive precedents exist in neuromyelitis optica caused by AQP4 autoantibodies, where the antiviral agent arbidol can serve as such a small blocking molecule, or ‘aquaporumab’ as a competitive and protective antibody." (PMID 29053777, 2018). "Aquaporin-4 (AQP4) autoimmunity is associated with the central nervous system (CNS) astrocyte disorder neuromyelitis optica spectrum disorder (NMOSD)." (PMID 29755396, 2018). "Autoantibodies to aquaporin-4 (AQP4) are pathogenic in neuromyelitis optica spectrum disorder (NMOSD)." (PMID 29447335, 2018).